CEP55 (centrosomal protein 55)
Diseases named in the same sentence as CEP55 in open-access papers (continued):
Sharing a sentence is not in itself a finding about the gene and the disease.
uveal melanoma (2 papers, 2023). A melanoma derived from melanocytes of the uveal tract. "Meanwhile, CEP55 protein levels were significantly highly expressed in all III stages of BRCA, HNSC, LUAD, PAAD, KIRC, and uveal melanoma (UVM), except for PAAD and KIRC in the II stage, where CEP55 levels were significantly elevated compared to control protein levels." (PMID 37887301, 2023). "Moreover, patients with recurrences during follow-up showed increased expression of CEP55 in ACC, KIRP, KICH, LIHC, LGG, PRAD, pheochromocytoma and paraganglioma (PCPG), UCEC, SARC, and uveal melanoma (UVM), and reduced expression in STAD." (PMID 37484531, 2023).
anencephaly (1 paper, 2025). A rare neural tube defect during pregnancy, resulting in the absence of a large portion of the brain and skull in the fetus. "Numerous studies have demonstrated that alterations in CEP55 expression or mutations are associated with a spectrum of diseases, including a genetic disorder predominantly characterized by anencephaly." (PMID 40918457, 2025).
Atrophy (1 paper, 2020). Any weakening or degeneration, especially through lack of use. "In contrast, Cep55 mutant zebrafish show renal atrophy during development." (PMID 32269212, 2020).
colon adenocarcinoma (1 paper, 2021). "Besides, by analyzing the relationship between CEP55 and some clinicopathological features of colon adenocarcinoma (COAD) and rectum adenocarcinoma (READ) patients, we found that in COAD, the expression of CEP55 in tumor patients over 40 years old increased with age." (PMID 33190424, 2021).
dengue (1 paper, 2023). "The GO analysis revealed that the genes BUB1, RRM2, IFI27, DLGAP5, and CEP55 exhibit 4-fold up-regulation in dengue and SD patients however, they exhibit downregulation in CP." (PMID 38076406, 2023).
gastric adenocarcinoma (1 paper, 2025). "Also, the sensitivity and specificity of the expression changes of the AURKA, CEP55, DTL, and TTK genes for distinguishing colorectal and gastric adenocarcinoma from normal tissue were evaluated by ROC analysis." (PMID 40723362, 2025).
gastric tumor (1 paper, 2025). "The violin plot showed that the expression levels of the AURKA, CEP55, DTL, and TTK genes were significantly increased in colorectal and gastric tumor tissues (p value < 0.05)." (PMID 40723362, 2025).
lung squamous cell carcinoma (1 paper, 2023). "The expression level and clinical relevance of CEP55 in cancers were verified in lung squamous cell carcinoma using in-house and multi-center samples (SMD = 4.07; AUC > 0.95; p < 0.05)." (PMID 37173675, 2023). "CEP55 may be an immune-related predictive and prognostic marker for multiple cancers, including lung squamous cell carcinoma." (PMID 37173675, 2023). "An extensive investigation of lung squamous cell carcinoma (LUSC), based on internal tissue microarrays and multi-center samples, was also performed to validate the clinical significance of CEP55 in cancers." (PMID 37173675, 2023).
lymphoma (1 paper, 2020). A malignant (clonal) proliferation of B- lymphocytes or T- lymphocytes which involves the lymph nodes, bone marrow and/or extranodal sites.
oropharyngeal squamous cell carcinoma (1 paper, 2021). "Here, we observed that USP9X-depleted HeLa and UMSCC74A oropharyngeal squamous cell carcinoma cells have reduced levels of CEP55 and CEP131." (PMID 34277417, 2021).
ovarian tumors (1 paper, 2016). "Taken together, these observations suggested that aberrant CEP55 expression was associated with the clinical development of primary ovarian tumors." (PMID 26615423, 2016).
pulmonary fibrosis (1 paper, 2024). Chronic progressive interstitial lung disorder characterized by the replacement of the lung tissue by connective tissue, leading to progressive dyspnea, respiratory failure, or right heart failure. "The autophagy gene Cep55 is associated with bleomycin-induced pulmonary fibrosis." (PMID 39764456, 2024).
septicemia (1 paper, 2021). "It has been reported that the expression of CEP55 in peripheral blood cells is significantly up-regulated in septicemia and abdominal infection that caused by bacterial infection, which means that bacterial infection could increase the expression of CEP55." (PMID 34650590, 2021).
small cell lung carcinoma (1 paper, 2024). Small cell lung cancer (SCLC) is a highly aggressive malignant neoplasm, accounting for 10-15% of lung cancer cases, characterized byrapid growth, and early metastasis. "CEP55 was determined to be one of the critical chromosomal instability signatures in breast, ovarian, and small-cell lung cancer." (PMID 38250876, 2024).
sterility (1 paper, 2020). "We have previously reported a Cep55-overexpression mouse model that exhibits male-specific sterility by suppressing Foxo1 nuclear retention through hyperactivation of Pi3k/Akt signaling." (PMID 33087841, 2020).
tongue cancer (1 paper, 2025). A malignant neoplasm affecting the tongue. "Among these, four genes (LY6K, ATAD2, CEP55, and MAGEA3) emerged as the most predictive of nodal spread specifically in tongue cancer." (PMID 41009820, 2025).
ulcerative colitis (1 paper, 2022). An inflammatory bowel disease involving the mucosal surface of the large intestine and rectum. "Our findings indicated that DPP10, MST1L, DPP10‐AS1, CEP55, ACSL1, MGP, OLFM4, and SGK1 may act as diagnostic biomarkers for ulcerative colitis and that differential immune infiltration cells may help to illustrate the progression of ulcerative colitis." (PMID 34939750, 2022). "Compared with the normal group, the expression of SGK1, CEP55, ACSL1, OLFM4, and MGP was markedly increased in the DSS‐induced ulcerative colitis group." (PMID 34939750, 2022). "To further validate these biomarkers' expression in ulcerative colitis, we determined mRNA levels of SGK1, CEP55, ACSL1, OLFM4, and DPP10 in lipopolysaccharides (LPS)‐stimulated Raw264.7 cells by quantitative reverse transcription‐polymerase chain reaction." (PMID 34939750, 2022). "To further validate the expression of these candidate biomarkers in ulcerative colitis, we determined mRNA levels of SGK1, CEP55, ACSL1, OLFM4, and DPP10 in LPS‐stimulated Raw264.7 cells by qPCR in in vitro bioassays." (PMID 34939750, 2022).
uterine corpus endometrial carcinoma (1 paper, 2023). A endometrial carcinoma (disease) that involves the body of uterus. "The highest CEP55 alteration frequency of 6.24% (33/529) was present in uterine corpus endometrial carcinoma, where the most mutations were present." (PMID 37887301, 2023).
ZIKV infection (1 paper, 2018). "Genes associated with cell differentiation and proliferation, such as BUB1, DLGAP5, PBK and CEP55 (Cluster 3) were upregulated during DENV infection but not ZIKV, while EGR1, HBEGF and MAFB (Cluster 4), were up-regulated at d17 POS during ZIKV infection." (PMID 30596671, 2018).
cancer (91 papers, 2008 to 2026). A tumor composed of atypical neoplastic, often pleomorphic cells that invade other tissues. "Elevated expression of CEP55 has been implicated in the tumorigenesis of diverse cancers, including endometrial cancer, bladder cancer, and clear cell renal cell carcinoma." (PMID 39871389, 2025). "In BC, upregulation of CEP55 has been associated with the malignant growth of cancer cells, exhibiting oncogenic properties." (PMID 39871389, 2025). "Altogether, our integrative TCGA data analysis shows that CEP55 expression is consistently elevated in multiple cancer types, and overexpression of CEP55 is negatively associated with immune cell infiltration." (PMID 38250876, 2024). "CEP55 has been discovered as both a cancer-associated antigen as well as a cancer–testis antigen, whereas the latter are proteins that are ordinarily expressed in the testes, but their expression becomes more widespread in cancers." (PMID 37175004, 2023). "We used a combined form of several databases to validate the expression of CEP55 in pan-cancer and its association with immune infiltration, and we further screened its targeted inhibitors with CEP55." (PMID 37887301, 2023). "CEP55 has been identified as a critical factor in cellular abscission, and further research revealed that it is abnormally expressed in various cancers and is implicated in cancer cell proliferation, invasion, and migration." (PMID 37484531, 2023). "To explore the association between CEP55 expression in multiple cancers and clinicopathological features, we first assessed CEP55 expression in patients with stage I, II, III, and IV cancers by TCGA cancer type." (PMID 37887301, 2023). "CEP55 expression was relevant to tumor mutation burden, microsatellite instability, neoantigen counts, and the immune microenvironment in various cancers (p < 0.05)." (PMID 37173675, 2023). "Aberrant expression of CEP55 has been strongly associated with clinical features and prognoses in cancer patients, which has led to an increasing interest in this molecule as a possible therapeutic target." (PMID 37484531, 2023). "CEP55 takes part in cytokinesis, and its abnormal expression is associated with genomic instability, a hallmark of cancer." (PMID 37175004, 2023). "In our analysis, both maintenance methylation (DNMT1, DNMT2) and de novo methylation (DNMT3a, DNMT3b) were found to be significantly associated with pan-cancer, resulting in the methylation of CEP55 at positions cg25827255, cg25314624, and cg04026927." (PMID 37887301, 2023). "Centrosomal protein 55 (CEP55) is a centrosome- and midbody-associated protein that is overexpressed in several cancers." (PMID 34104194, 2021). "Clinically, Cep55 has also been found to be overexpressed in many cancer types, and its overexpression has been strikingly associated with tumor stage and metastasis." (PMID 34650590, 2021). "Growing evidence indicates the association between CEP55 upregulation and the development and progression of a variety of malignant tumors, including breast tumors, gastric tumors, and lung tumors." (PMID 32337246, 2020). "Related clinical studies have shown that CEP55 can be used as a diagnostic and prognostic marker for several cancers." (PMID 32437446, 2020). "Though these in vitro and clinical correlation studies have so far established the link between CEP55 overexpression and cancer, the underlying mechanism by which CEP55 promotes tumorigenesis in vivo remains elusive." (PMID 33087841, 2020). "Collectively, these data highlight that Cep55 overexpression alone is sufficient to drive tumorigenesis in mice, causing a broad spectrum of cancers and associated with metastasis." (PMID 33087841, 2020).
cancer (continued). "In multiple human cancers, deregulated expression of CEP55 has been linked to enhanced proliferation, migration, invasion, epithelial-mesenchymal transition, and tumorigenesis." (PMID 33087841, 2020). "Centrosomal protein 128 (CEP128) is part of the centrosomal protein family, including CEP55 that has been implicated in cancer progression." (PMID 30606113, 2019). "It has been found that CEP55 overexpression is significantly associated with tumor stage, invasiveness, and tumor metastasis of many malignant tumors." (PMID 31422942, 2019). "CEP55 is a component of a 70‐gene signature associated with chromosomal instability in several human cancers." (PMID 30108112, 2018). "Cell migration and invasion are directly associated with cancer metastasis; therefore, further studies are needed to confirm if and how CEP55 supports HCC metastasis in vivo by using orthotropic xenograft models." (PMID 30096813, 2018). "The centrosomal protein, CEP55, is a key regulator of cytokinesis, and its overexpression is linked to genomic instability, a hallmark of cancer." (PMID 30108112, 2018). "Curiously, two other highly disordered CTAs, NOL4 and CEP55, were shown to be associated with different types of cancer." (PMID 28362316, 2017). "Centrosomal protein 55 (CEP55) is a cell cycle regulator implicated in development of certain cancers." (PMID 26615423, 2016). "Therefore, the association between CEP55 expression levels and clinical characteristics (e.g., distant metastasis) of cancer patients was examined." (PMID 37173675, 2023). "To assess the genetic alteration of CEP55 in various cancers, we performed a mutational analysis using the cBioPortal database and found that CEP55 was altered in 1.3% (138/10,950) of patients with pan-cancer." (PMID 37887301, 2023). "The distinct CEP55 expression between cancers and controls implies that CEP55 may have underlying clinical significance in an extensive range of cancers." (PMID 37173675, 2023). "Notably, the stimulaotry gene, high mobility group box 1 (HMGB1), was significantly positively associated with CEP55 in all 33 cancers, suggesting involvement in CEP55-related ICP effects." (PMID 37887301, 2023). "In addition, we investigated the connections between CEP55 expression and hallmark cancer pathways, immune cell infiltration, and immune regulator expression across malignancies." (PMID 37484531, 2023). "CEP55 is an important regulator involved in cytoplasmic division, and its abnormal expression is clearly associated with genomic instability, which is an important sign of malignant tumors." (PMID 37274251, 2023). "For DSS, CEP55 can also be a risk factor for 12 cancers (ACC, etc.)." (PMID 37173675, 2023). "The high expression of the CEP55 protein was associated with worse outcomes in cancer treatments." (PMID 35517890, 2022). "Additionally, CEP55 overexpression is associated with genomic instability, and it is considered to be a cancer-associated protein." (PMID 35549631, 2022). "Many studies have demonstrated that CEP55 was highly expressed in a variety of cancers and could be used as a diagnostic and prognostic marker for several cancers." (PMID 34497684, 2021). "CEP55 overexpression has been linked with tumorigenesis for a wide variety of cancers." (PMID 33087841, 2020). "As an oncogene, up-regulation of CEP55 is also associated with poor prognosis in certain cancers." (PMID 32437446, 2020). "CEP55 is a tumor-associated antigen due to its aberrant expression in cancer." (PMID 32337246, 2020). "CEP55 is a 55 KD-sized centrosome-associated protein that plays an important role in membrane fission events and is a key regulator of cell division, and is closely related to the development of cancer." (PMID 32437446, 2020). "CEP55 is part of the 70‐gene chromosomal instability (CIN) signature that was associated with aneuploidy in several human cancers; thus, we questioned whether high CEP55 expression could confer tolerance to or promote aneuploidy (causal effect)." (PMID 30108112, 2018).
cancer (continued). "It is reported that the early upregulation of FOXM1 during head and neck cancer progression, rendering it as an attractive diagnostic biomarker for early cancer detection and its candidate mechanistic targets, CEP55 and HELLS, as indicators of malignant conversion and progression." (PMID 26615423, 2016). "CEP55 has been identified as a regulator required for cell cycle progression and completion of cytokinesis by loss-of-function studies and it is over-expressed in several cancer cell lines." (PMID 18714348, 2008). "Therefore, overexpressing CBX2 and CEP55 may cause cancer cells to develop cancer stem cell-like phenotypes with high levels of invasion, metastasis, and radiation resistance." (PMID 37980163, 2023). "In addition, CBX2 and CEP55 may enhance extracellular matrix reprograming via cancer-associated fibroblast." (PMID 37980163, 2023). "CEP55 was highly expressed across bulk and scRNA-seq datasets (cancer epithelial and CD8+ TEMRA cells) and negatively correlated with overall survival (OS) and progression-free survival (PFS)." (PMID 42195052, 2026). "Machine learning identified five potential diagnostic biomarkers (COLEC12, TMCC1, CEP55, KLK3, COL4A1) with an AUC of 0.903, which are implicated in immune modulation and cancer progression." (PMID 40427030, 2025). "Overexpression of CEP55 can lead to uncontrolled cell division and survival, contributing to cancer progression." (PMID 40723362, 2025). "Studies in other cancers have also shown that CEP55 primarily promotes tumorigenesis by affecting cell proliferation, apoptosis, migration, and invasion." (PMID 40386043, 2025). "Up‐regulation of Centrosomal Protein 55 (CEP55) in cancer cells increases malignancy, and the protein can be transferred via exosomes." (PMID 39976236, 2025). "A study from the TCGA database provided a comprehensive evaluation of cancer-testis antigen CEP55 expression in various cancers such as GBM." (PMID 40504854, 2025). "Our data show that CEP55 loading into exosomes of cancer cells is controlled by an unconventional Alix‐depending pathway that involves the ER and CD63 late endosomes." (PMID 39976236, 2025). "In the pan‐cancer scRNA‐seq data set, we isolated tumor epithelial cells for dimensionality reduction and clustering, demonstrating CEP55 expression in a subset of these cells." (PMID 40236779, 2025). "In summary, in addition to the centrosome, CEP55 also shows a dot‐like localization in cancer cells." (PMID 39976236, 2025). "They reported that CEP55 was a potential biomarker and was correlated with immune infiltration and immunotherapy efficacy in a pan-cancer study." (PMID 40504854, 2025). "Centrosomal Protein 55 (CEP55) is a cancer‐testis antigen whose expression is up‐regulated in a high number of cancer types." (PMID 39976236, 2025). "Centrosomal Protein 55 (CEP55) modulates mitotic fidelity and PI3K/AKT signaling, with dysregulation linked to various cancers and inflammatory disorders." (PMID 41614789, 2025). "To explore CEP55's biological functions, we utilized TCGA pan‐cancer datasets and scRNA‐seq data, revealing its enrichment in cell cycle‐related pathways, particularly the G2M CHECKPOINT and E2F TARGETS." (PMID 40236779, 2025). "In this study, we addressed this issue and showed that endogenous as well as overexpressed CEP55 appeared as dots in cancer cells." (PMID 39976236, 2025). "Studies have used correlation studies to highlight the link between CEP55 overexpression and cancers such as breast and osteosarcoma." (PMID 38250876, 2024). "During mitosis, PLK1 interacts and phosphorylates the N-terminus of SPAG5 (also known as astrin), which has been reported to upregulate the PI3K/AKT pathway in cancer cells in vitro through the centrosome protein CEP55." (PMID 38534420, 2024). "Consistent with previous studies, we found that CEP55 expression was upregulated in multiple cancer types." (PMID 38250876, 2024).